IL22 (interleukin 22)
Diseases named in the same sentence as IL22 in open-access papers (continued):
Sharing a sentence is not in itself a finding about the gene and the disease.
Arthritis (continued). "Local (joint) treatment of mice with a neutralizing antibody against IL-22 (injected simultaneously with mBSA) reduced joint nociception and neutrophil migration during arthritis development." (PMID 26330334, 2015). "For instance, the interdependence of IL-17 and IL-22 in other models of experimental arthritis has been suggested." (PMID 26330334, 2015). "Supporting these findings, the direct administration of recombinant murine IL-22 into the joints recapitulates the clinical (pain enhancement) and morphological (neutrophil migration) characteristics of arthritis." (PMID 26330334, 2015). "In agreement with our results, treatment with anti-IL-22 reduced inflammation and bone erosion in IL-1-driven arthritis." (PMID 26330334, 2015). "Previous reports have observed an increase in IL-22 expression in experimental models of arthritis in mice." (PMID 26330334, 2015). "Another important observation is that the pro-inflammatory role of IL-22 in joint inflammation appears to be dependent on ASC." (PMID 26330334, 2015). "Mice with arthritis scores of > or = 1 and arthritis duration of 4 days were randomized to receive anti-IL-22 antibody or isotype control antibody for a total of 10–12 days." (PMID 24676270, 2014). "In this report neutralization of endogenous IL-22 after onset of arthritis lead to reduced joint inflammation." (PMID 24676270, 2014). "Arthritic mice with scores of > or = 1 and arthritis duration of 4 days were randomized to receive anti-IL-22 antibody or isotype control for a total of 8–9 days." (PMID 24676270, 2014). "Our data shows that collagen specific IL-22 response expands with onset of arthritis and IL-22 producing cells are discrete from IL-17 or IFN-γ producing cells." (PMID 24676270, 2014). "Put together, these findings suggest that during arthritis IL-22 producing cells and the IL-22 response is more abundant in lymphoid organs in comparison to arthritic joints." (PMID 24676270, 2014). "We wanted to evaluate if the increased IL-10 responses seen with the protective function of IL-22 was blunted or reversed during arthritis." (PMID 24676270, 2014). "Recombinant IL-22 restrains progression of arthritis via increase in IL-10 responses when administered prior to onset of arthritis." (PMID 24676270, 2014). "In order to elucidate collagen specific IL-22 response during arthritis, splenocytes from naïve mice, mice from the initiation phase or arthritic mice were stimulated with collagen and IL-22 response was measured in culture supernatants by ELISA." (PMID 24676270, 2014). "Experiments outlined here were designed to elucidate the contribution of endogenous IL-22 before and after the onset of arthritis." (PMID 24676270, 2014). "Neutralization of IL-22 after onset of arthritis resulted in significant increase in Th1 responses and significantly reduced severity of arthritis." (PMID 24676270, 2014). "In keeping with the therapeutic effect of anti-IL-22, when administered after the onset of arthritis, IgG2a anti-collagen antibodies are significantly but modestly reduced and IgG1 and IgG2b antibodies are unaltered in mice receiving anti-IL-22." (PMID 24676270, 2014). "In our previous report administration of recombinant IL-22 prior to onset of joint inflammation increased IL-10 responses and restrained the progression of arthritis." (PMID 24676270, 2014). "In order to elucidate if the protective effect of anti-IL-22 is dependent on IFN-γ, we induced arthritis in IFN-γ deficient mice." (PMID 24676270, 2014). "Anti-IL-22 antibody or isotype control were administered prior to or after onset of arthritis and disease progression assessed by clinical scoring and histopathology." (PMID 24676270, 2014). "In our previous study we reported that administration of recombinant IL-22 prior to the onset of arthritis reduces the severity of subsequent arthritis via increase in IL-10, implying a possible protective role of IL-22 during this phase." (PMID 24676270, 2014).
Arthritis (continued). "Collagen specific IL-22 responses were expanded during arthritis and IL-22 producing cells were discrete from IL-17 or IFN-γ producing cells." (PMID 24676270, 2014). "In order to elucidate the role of neutralizing IL-22 before onset of arthritis, anti-IL-22 antibody or isotype control was administered to mice from day 18 following immunization with collagen for a total of 8–10 days." (PMID 24676270, 2014). "Previous studies have reported that IL-22 is induced in lymphoid organs during arthritis and produced by CD4 T cells and/or CD49b+ cells." (PMID 24676270, 2014). "In our current study we show that neutralization of IL-22 prior to onset of joint inflammation, augments arthritis supporting a protective role of IL-22 during this phase." (PMID 24676270, 2014). "Persistent blocking of IL-23 activity before inducing the AIA flare-up significantly prevented the expression of severe joint inflammation with lower synovial mRNA expression of IL-17A and IL-22." (PMID 23469022, 2013). "Anti IL-17 and IL-22 suppressed arthritis, reminiscent of the SKG experience, and IL-22 gene minicircles could drive enthesitis and new bone formation." (PMID 40938333, 2025). "Furthermore, administration of both the AHR agonist VAG53927 enhancing IL‐22, and rIL‐22 attenuated serum transfer arthritis." (PMID 33734594, 2021). "Notably, normal mice before the onset of RA showed a higher incidence and severity of arthritis after receiving anti-IL-22 treatment." (PMID 33407883, 2021). "IL‐22 could conceivably exacerbate arthritis as the disease evolves to irreversible joint deformity." (PMID 29713472, 2018). "Conversely, IL-22 administration in CIA mice inhibits arthritis through enhanced IL-10 expression." (PMID 30619268, 2018). "And it seems that IL-22 plays a proinflammatory role in the pathogenesis of arthritis." (PMID 29182672, 2017). "Some researches show the relationship of IL-22 and arthritis animal models." (PMID 29182672, 2017). "However, it is still unclear how IL-22 induce tissue inflammation and autoimmunity, and other biological functions of IL-22 in arthritis." (PMID 29182672, 2017). "These major differences are treating IL-22 in different time points of arthritis." (PMID 29182672, 2017). "It is supposed that a significantly activated on the IL-22 signaling pathway playing a critical role in arthritis pathogenesis and IL-22 might aggravated the severity of PIA." (PMID 29182672, 2017). "This research revealed that the signaling pathway of IL-22 may be activated in arthritis pathogenesis." (PMID 29182672, 2017). "Reduced production of T cell-polarizing cytokines such as IL-6 and IL-23 by myeloid pten-/- APCs in vitro as well as in vivo after induction of CIA leads to reduced generation of IL-17- and IL-22-producing T cells, which in turn are required to induce arthritis in CIA animals." (PMID 26307404, 2015). "Next, we developed a model of zymosan-induced arthritis in IL-22−/− mice to evaluate whether the reduction of AIA in IL-22−/− mice is a specific phenotype or a consequence of strain manipulation." (PMID 26330334, 2015). "In addition, in the experimental model of spontaneous arthritis observed in IL-1 receptor antagonist (Ra) −/− mice, the level of IL-22 was shown to be upregulated in inflamed synovial tissue." (PMID 26330334, 2015). "Our findings also suggest that the pro-inflammatory role of IL-22 in the physiopathology of arthritis is dependent on the modulation of IL-1β production in the joint, which may be dependent on ASC." (PMID 26330334, 2015). "In arthritis patients and controls, IL‐17 production and Th17‐associated surface markers are greatly enriched in CD146+CD4 cells, but the functional repertoire of CD146+CD4 cell populations includes secretion of IL‐22 and IFN‐γ, alone or with IL‐17." (PMID 25113810, 2015). "Therefore, it seems that IL-22 is a possible therapeutic target in the initial phase of RA, controlling the various symptoms present in arthritis." (PMID 26330334, 2015).
Arthritis (continued). "This is in keeping with the overall protective role of IFN-γ in CIA and a recent study reporting selective deficiency of Ahr, a transcription factor for IL-22, in CD4 T cells being associated with reduced arthritis and increased Th1 response but an unaltered Th17 response." (PMID 24676270, 2014). "The reduction in arthritis in p19-deficent mice induced by the i.p. route may thus be due to IL-22 or other inflammatory cytokines induced by IL-23." (PMID 25253467, 2014). "This is in keeping with lower arthritis severity in mice receiving anti-IL-22 in comparison to isotype control.IL-17 was undetectable when joints cells were stimulated with collagen (data not shown), perhaps due to the low numbers of antigen specific cells in joints." (PMID 24676270, 2014). "IL-22 deficient mice had similar degree of arthritis as wild type mice in a model where joint inflammation was induced after local injection of mBSA into joints, suggesting that IL-22 is not pathogenic in the absence of prolonged systemic inflammation." (PMID 24676270, 2014). "Additionally, neutralization of IL-22 prior to onset of arthritis resulted in increased incidence and severity of arthritis, supportive of a protective effect of IL-22 prior to onset of arthritis." (PMID 24676270, 2014). "The protective effect of anti-IL-22 is blunted in IFN-γ deficient mice, indicating that increased IFN-γ responses associated with the administration of anti-IL-22 plays a dominant role behind its protective function during arthritis." (PMID 24676270, 2014). "Furthermore, administration of recombinant IL-22, prior to the onset of arthritis, reduces the progression to severe arthritis in the model of CIA." (PMID 24676270, 2014). "Put together, these findings imply that IL-22 may play a dual role in arthritis depending on the phase of arthritis." (PMID 24676270, 2014). "IL-22R1 is upregulated in T cells during arthritis and IL-22 regulated IFN-γ in-vitro and in-vivo." (PMID 24676270, 2014). "In the IL-1receptor antagonist deficient mice, neutralization of IL-22 after arthritis onset reduced bone damage without any change in overall inflammation." (PMID 24676270, 2014). "Mice receiving anti-IL-22 had increased incidence and severity of arthritis." (PMID 24676270, 2014). "Put together, antigen specific IL-22 response is induced with onset of arthritis." (PMID 24676270, 2014). "Collagen restricted IL-22 response was augmented during arthritis." (PMID 24676270, 2014). "Finally, VAG539 injections in K/BxN‐treated Il‐22 deficient mice did not improve arthritis symptoms, demonstrating that IL‐22 production is required downstream of AHR activation to promote protective effects." (PMID 33734594, 2021). "The resulting arthritis could be partially blocked with monoclonal antibodies against IL-17A and IL-22 and appeared to involve an enthesis-resident IL-23 receptor expressing CD3+CD4−CD8− T cell population, which produced IL-17A and IL-22 when stimulated with IL-23 in vitro." (PMID 33983951, 2021). "Supporting the anti-inflammatory role of PRL in arthritis, PRL-receptor-null mice exhibited increased joint swelling and higher joint expression of the genes encoding for TNFα, IL-1β, IL-6, IFNγ, IL-17A, IL-21, IL-22, IL-23, and IL-10 when subjected to monoarticular AIA (MAIA)." (PMID 28506283, 2017). "Therefore, we concluded that IL-22 was significantly increased in the process of rat arthritis." (PMID 29182672, 2017). "Furthermore, neutralization of IL-22 after the onset of CIA diminished the severity of arthritis." (PMID 26330334, 2015). "Furthermore, the correlation of IL-17 and IL-22 was also observed in patients with arthritis." (PMID 26330334, 2015). "Moreover, administration of anti-IL-22 prior to onset of arthritis augmented arthritis severity." (PMID 24676270, 2014).
Arthritis (continued). "This was in contrast to arthritic mice that underwent an arthritis flare-up since a significantly lower disease score was observed in the IL-23p19 treated mice compared to the control group, accompanied by lower synovial IL-17A and IL-22 expression in the knee joints of these mice." (PMID 23469022, 2013). "Elimination of microbiota after the onset of arthritis resulted in suppression of intestinal SAA1, SAA2 and IL-22 expression and a specific reduction of LP Th17 cells accompanied with reduced Th17 cell abundance in joint-draining lymph nodes of the CIA mice." (PMID 29142301, 2017). "Daily administration of recombinant IL-22 starting before onset of arthritis reduces disease severity of CIA in DBA mice but does not alter incidence." (PMID 33692792, 2021). "We first noted an increased expression of the Ahr gene in the synovium 24h after serum injection before the appearance of clinical signs of arthritis, which likely accounts for increased expression of known AHR‐dependent target genes expression such as Il‐22 and Cyp1a1." (PMID 33734594, 2021). "H&E stained sections of wrists confirmed the absence of arthritis in IL-23 EEV injected B6 mice compared to the susceptible B10.RIII strain, and there was no significant induction of Tnf, Il1b, Il17a or Il22 in the wrists of IL-23 EEV injected B6 mice." (PMID 33983951, 2021). "Moreover, CD4+T cells isolated from arthritic joints and splenocytes express IL-22 after the induction of AIA, suggesting the possible involvement of IL-22 in this model of arthritis." (PMID 26330334, 2015). "On day 13 after pristane injection, mRNA expression of Il17 and the Th17-associated cytokine, Il22, was approximately 60–80-fold higher in CD4+ T cells from inguinal than mesenteric LNs, which drains the intestine but not the joints, and whose T cells do not transfer arthritis." (PMID 32345366, 2020). "In this model, synovial expression of IL-17A and IL-22 but not IFN-γ was lower in the anti-IL-23p19 group compared to control, highlighting the role of IL-23 in memory T cell driven flare-up arthritis." (PMID 23469022, 2013). "In this model, synovial expression of IL-17A and IL-22 but not IFN-γ was markedly lower in the anti-IL-23p19 group compared to control, highlighting the role of IL-23 in memory T cell driven flare-up arthritis." (PMID 23469022, 2013). "The incidence of arthritis and pannus went down in the CIA rats without IL-22." (PMID 31828174, 2019).
hepatocellular carcinoma (45 papers, 2011 to 2025). A malignant tumor that arises from hepatocytes. "Th17 down-regulation by metformin has also been demonstrated in a hepatocellular carcinoma model associated with a decrease in IL-22 secretion, as well as a transient increase in Treg cells in a leukemia solid tumor model." (PMID 29899823, 2018). "This study focused on the association of IL-10RB K47E with the effects of IFN-λ and IL-22 in cultured hepatoma cells." (PMID 23519428, 2013). "The best-studied member of the family in inflammatory balance of the liver is the IL-22 cytokine, which on the one hand may have a protective role in fibrosis progression but on the other may induce liver tissue susceptibility in hepatocellular carcinoma development." (PMID 29892294, 2018). "HBV replication in hepatoma cells expressing IL-10RB K47 or E47 in response to IFN- λ or IL-22 was determined to explore whether the single nucleotide polymorphism of an IL-10RB extracellular domain affects the cellular response to IL-22 and IFN-λ." (PMID 23519428, 2013). "The biological role of IL-22 was originally described in hepatoma cells, keratinocytes, and pancreatic acinar cells, and it was subsequently reported to be involved in the pathogenesis of numerous inflammatory diseases, notably psoriasis." (PMID 35054942, 2022). "The related consequences of high levels of IL-22 have been fully illustrated in the diethylnitrosamin induced hepatocellular carcinoma model, where IL-22 transgenic mice show increased and IL–22-/- mice decreased tumor formation." (PMID 35967401, 2022). "Downstream of its receptor, effects of IL-22-signaling are mediated by activation of signal transducer and activator of transcription (STAT) 3, although STAT1 and STAT5 can be equally phosphorylated in hepatoma cells upon IL-22-stimulation." (PMID 33851257, 2021). "Hence, considering that systemic injections of IL-22 increase the risk of hepatocellular carcinoma in patients with CLD, altering the gut microbiota to regulate the immune cells that produce IL-22 may offer a more viable option for liver injury therapeutic interventions." (PMID 33869241, 2021). "IL-22 has recently been proposed as a target for cancer therapy as its increased expression has been reported in colonic, gastric, and hepatocellular cancer, as well as in small- and large-cell lung carcinoma." (PMID 31935914, 2020). "Excessive IL-22 levels were also noted in a prior study in infiltrated leukocytes of a hepatocellular carcinoma patient." (PMID 31935914, 2020). "Hepatocellular carcinoma (HCC) tumor-infiltrating lymphocytes (TILs) are reported to be enriched with IL-22 in consort with elevated expression of IL-23 and IL-22BP in cancerous tissue." (PMID 33042126, 2020). "At present, studies focus on the main role of IL-22 in the liver, which is protection against liver damage in chronic diseases and hepatocellular carcinoma." (PMID 31749919, 2019). "The gene expression analysis of the IL-22-treated HepG2 cells (human hepatocellular carcinoma line) identified PLA2G2A as an upregulated antimicrobial protein in the pathogen infection study." (PMID 31461453, 2019). "In contrast, inability of IL-22 to activate Erk/1/2 has been shown in a human hepatoma cell line HepG2 and primary epithelial cells isolated freshly from human and mouse colons." (PMID 29075900, 2018). "Nonetheless, IL-22 can also promote tumor growth both in vitro and ex vivo, and its levels are increased in patients with hepatocellular carcinoma." (PMID 29892294, 2018). "While T cells as source of IL-22 in lung cancer have not been proposed prior to our study, our data are supported by evidence from other tumor types such as colon, gastric or hepatic carcinomas where CD4 T cells are thought to be the main sources of IL-22." (PMID 27388918, 2016). "In hepatocellular carcinoma, tumor infiltrated leukocytes were significantly enriched in IL-22 expressing cells." (PMID 25793261, 2015).